CD200 (CD200 molecule)
Diseases named in the same sentence as CD200 in open-access papers (continued):
Sharing a sentence is not in itself a finding about the gene and the disease.
brain tumors (4 papers, 2014 to 2024). "CD200 is overexpressed in various subgroups of human brain tumors, including glioblastoma, medulloblastoma, ependymoma, and neuroblastoma." (PMID 37894750, 2023). "We found increased expression of CD200 mRNA in multiple human brain tumors as well as increased soluble CD200 (sCD200) concentrations in the sera of patients as their tumors progressed." (PMID 25598973, 2014). "Given these initial findings, we next compared CD200 mRNA levels in a larger cohort of brain tumors relative to normal brain and meningioma (MEN), an extra-axial tumor arising in the lining of the CNS, not a true brain tumor." (PMID 25598973, 2014). "Because of the homology between mouse and human CD200, our data also suggest that blockade of CD200 binding to its receptor will enhance the efficacy of immune mediated anti-tumor strategies for brain tumors." (PMID 25598973, 2014). "We found CD200 protein expressed on a variety of human brain tumor tissue samples by western analysis: anaplastic oligoastrocytoma (n = 1), GBM (n = 3), meningioma (n = 1), ependymoma (n = 2), oligodendrogliomas (n = 1) and pilocytic astrocytoma (n = 1)." (PMID 25598973, 2014). "The amount of circulating CD200 protein in the sera of patients with brain tumors was determined by ELISA and, when corresponding peripheral blood samples were available, was correlated quantitatively with MDSCs." (PMID 25598973, 2014). "CD200 mRNA expression levels in human brain tumor tissue samples were measured by microarray." (PMID 25598973, 2014). "The survival of GL261 glioma tumor-bearing mice increased, suggesting that disrupting the binding between CD200 and its receptor, CD200R, can potentially enhance the efficacy of an immune-mediated antitumor approach for brain tumors." (PMID 37894750, 2023). "The crucial checkpoints in pediatric brain tumors are cytotoxic T lymphocyte antigen-4 (CTLA-4), programmed cell death protein-1 (PD-1) and programmed death-ligand 1 (PD-L1), OX-2 membrane glycoprotein (CD200), and indoleamine 2,3-dioxygenase (IDO)." (PMID 37605389, 2024). "It was not surprising that brain tumors, due to the origin of the cells, had high expression levels of CD200." (PMID 25598973, 2014).
ischemia (4 papers, 2020 to 2025). A hypoperfusion of the BLOOD through an organ or tissue caused by a PATHOLOGIC CONSTRICTION or obstruction of its BLOOD VESSELS, or an absence of BLOOD CIRCULATION. "In the CA3 field of the ischemia group, the change in CD200 level triggered by tFI was similar with those in the hippocampal CA1 field until 12 h after tFI (79.1% at 6 h and 114.4% at 12 h post-tFI compared to those in the sham group)." (PMID 33498705, 2021). "In the ischemia group, CD200 immunoreactivity was apparently changed in pyramidal cells of the CA1 field." (PMID 33498705, 2021). "In the MCAO/R groups, CD200/NeuN expression increased at 1 day and then decreased depending on the time after ischemia/reperfusion occurred." (PMID 33067924, 2020). "In the ischemia group, CD200 level was remarkably altered in the CA1 field." (PMID 33498705, 2021). "In the ischemia/RIS group, CD200 immunoreactivity in the CA1 field was not altered until 12 h after tFI (Cc and D)." (PMID 33498705, 2021).
myelodysplastic syndrome (4 papers, 2020 to 2023). A clonal hematopoietic disorder characterized by dysplasia and ineffective hematopoiesis in one or more of the hematopoietic cell lines. "This study was designed in order to identify the prognostic relevance of CD200 expression and soluble Cytotoxic T-lymphocyte antigen-4 (CTLA-4) levels in myelodysplastic syndrome (MDS) patients." (PMID 32856848, 2020).
non-small cell lung carcinoma (4 papers, 2023 to 2025). A group of at least three distinct histological types of lung cancer, including non-small cell squamous cell carcinoma, adenocarcinoma, and large cell carcinoma. "CD200 is a target of miR-499a and a polymorphism in miR-499a is a poor prognostic factor for non-small cell lung cancer cases who also exhibit elevated CD200 expression." (PMID 36738455, 2023).
androgenetic alopecia (3 papers, 2012 to 2025). "The bald scalps of men with androgenetic alopecia lack CD200-rich, CD34-positive hair follicle progenitor cells, and have a defect in conversion of hair follicle stem cells to progenitor cells, which play a role in the pathogenesis of androgenetic alopecia." (PMID 22506014, 2012). "K15 was found at normal levels of non-productive hair follicles of bald scalp from men with androgenic alopecia, but CD34 and CD200 were markedly diminished suggesting a failure of the conversion from K15-positive stem cells to CD34- and CD200-positive hair progenitor cells." (PMID 23799033, 2013).
cervical carcinoma (3 papers, 2021 to 2022). A carcinoma arising from either the exocervical squamous epithelium or the endocervical glandular epithelium. "Thus, keratinocyte carcinoma CD200 expression, whether in cervical carcinoma or BCC, promotes tumor growth." (PMID 36074574, 2022). "In addition, by specifically analysing various immune checkpoints, we identified a significant upregulation of the immunosuppressive CD200 molecule, which might serve as a potential immunotherapeutic target in chemo-treated cervical cancer." (PMID 33087896, 2021).
colorectal cancer (3 papers, 2019 to 2024). A primary or metastatic malignant neoplasm that affects the colon or rectum. "Notably, a strong association between CD200 expression and activation of Wnt/β-catenin pathway has been recently described in colorectal cancer." (PMID 30132130, 2019). "In addition to validating the high expression of CD200 in endothelial cells in bioletters, flow cytometry also found that epithelial cells and CD4+ T cells also expressed CD200 in three tumors, and fibroblasts in colorectal cancer were highly expressed CD200." (PMID 39120585, 2024). "Nevertheless, because the colorectal cancer model MC38 expressed PD-L1 as well as CD200, and more complete responses were observed when both receptors were blocked, this supports the possibility that CD200 expression on tumour cells might indeed contribute to the inhibition of TIICs in vivo." (PMID 37082107, 2023).
COVID-19 (3 papers, 2021 to 2024). A disease caused by infection with severe acute respiratory syndrome coronavirus 2. "In addition, the levels of IL-5Rα, FABP2, CD200 and transferrin consistently showed the highest levels in the moderate group, indicating that these factors may serve as sensitive biomarkers reflecting COVID-19 disease severity." (PMID 34335566, 2021). "Finally, a total of eleven differential factors related to COVID-19 disease severity were identified, including: TRAIL R1, IGFBP-1, IGFBP-4, VCAM-1, sFRP-3, FABP2, Transferrin, GDF15, IL-1F7 (also known as IL-37), IL-5Rα, and CD200." (PMID 34335566, 2021).
craniosynostosis (3 papers, 2021 to 2022). Craniosynostosis is defined as the premature fusion of one or more cranial sutures leading to secondary distortion of skull shape resulting in skull deformities with a variable presentation. "We identified a uniquely downregulated cluster of genes in PF-CD51+;CD200+ cells which are associated with craniosynostosis." (PMID 34330896, 2021). "We identify that aberrancies in CD51+;CD200+ cell equilibrium may underlie both physiologic suture closure and pathologic craniosynostosis." (PMID 34330896, 2021). "Wnt activation increased CD51+CD200+ cells and rescued craniosynostosis by preventing suture closure." (PMID 36261411, 2022). "The different trends of resident CD51+;CD200+ cells between physiologically fusing versus patent sutures set the stage for investigating these cells in syndromic and non-syndromic craniosynostosis." (PMID 34330896, 2021). "Furthermore, we demonstrate that cWnt activation increases CD51+;CD200+ cell frequency, prevents suture fusion, and ultimately rescues the craniosynostosis phenotype." (PMID 34330896, 2021). "CD51+;CD200+ cells are then prospectively isolated from physiologically fusing and patent sutures, in addition to cranial sutures harvested from animal models of syndromic and non-syndromic craniosynostosis." (PMID 34330896, 2021). "The population of CD51+;CD200+ cells is also significantly reduced in Twist1+/− mice before suture fusion defects occur, although it remains unknown whether ablation of this cell population leads to craniosynostosis in mice." (PMID 35451466, 2022). "It will be informative to determine the feasibility and efficacy of this heterogenous suture MSC population in treating craniosynostosis, including Axin2+, Prrx1+, Ctsk+ and CD51+;CD200+ cells." (PMID 35451466, 2022). "Having phenocopied a SAG model of non-syndromic craniosynostosis, we next performed FACS profiling of CD51+;CD200+ cells." (PMID 34330896, 2021). "Collectively, these data support that cWnt activation in the suture mesenchyme of the Twist1+/−:Axin2lacZ/+ COR suture may suppress COR suture craniosynostosis observed in Twist1+/− mice, possibly through expansion of the CD51+;CD200+ cell population." (PMID 34330896, 2021). "This study examined cranial suture biology through the lens of a skeletal stem/progenitor cell population (namely CD51+;CD200+), demonstrating a link between, CD51+;CD200+ cell equilibrium and cranial suture patency, thus highlighting the potential significance of these cells in craniosynostosis." (PMID 34330896, 2021).
gastric cancer (3 papers, 2022 to 2023). A primary or metastatic malignant neoplasm involving the stomach. "The proportion of T lymphocytes expressing CD200 is higher in patients with gastric cancer than that in healthy controls." (PMID 37894750, 2023).
inflammatory bowel disease (3 papers, 2016 to 2022). A spectrum of small and large bowel inflammatory diseases of unknown etiology. "We investigated the effect of "knockout"of CD200 or CD200R, or over-expression of CD200, on susceptibility to dextran sodium sulfate (DSS)—induced colitis, a mouse model of inflammatory bowel disease (IBD)." (PMID 26841120, 2016).
lung adenocarcinoma (3 papers, 2017 to 2023). A carcinoma that arises from the lung and is characterized by the presence of malignant glandular epithelial cells. "This was evidenced by decreased cell viability of lung adenocarcinoma cells when CD200+ CAFs were cocultured with gefitinib." (PMID 38137547, 2023). "Immunohistochemical analysis of samples from patients receiving postoperative gefitinib treatment revealed that the individuals whose resected lung adenocarcinomas contained CD200-positive CAFs tended to have longer progression free survival of gefitinib when they recurred after surgery." (PMID 28429795, 2017).
metastatic tumors (3 papers, 2012 to 2020). "However, in that study it was unclear if expression of CD200 on metastatic tumors was responsible for tumor metastasis." (PMID 22319630, 2012). "Previously using flow cytometry and IHC, we showed that 4THM cells as well as metastatic tumors originated from 4THM primary tumors do not express CD200." (PMID 29721190, 2018).
pancreatic ductal adenocarcinoma (3 papers, 2021 to 2023). An infiltrating adenocarcinoma that arises from the epithelial cells of the pancreas. "In liver metastases from primary pancreatic ductal adenocarcinoma, CD200 and BTLA pathways can drive macrophage-mediated adaptive immune tolerance." (PMID 37143720, 2023). "Our results point to CD8 and FAP as potential prognostic biomarkers and demonstrate the heterogeneous expression pattern of CD200 in patients with pancreatic ductal adenocarcinoma." (PMID 34771664, 2021).
Sepsis (3 papers, 2012 to 2022). Sepsis is defined as life-threatening organ dysfunction caused by a dysregulated host response to infection. "Indeed, previous work has shown that CD200−/− mice show increased numbers of activated leukocytes and pro-inflammatory cytokines and higher mortality in response to experimental septicemia." (PMID 30777093, 2019).
skin cancer (3 papers, 2017 to 2023). "Recent studies have also reported CD200 expression across hematologic malignancies, solid tumors, and skin cancers." (PMID 38137547, 2023). "Merkel cell carcinoma (MCC), a rare and aggressive form of skin cancer, exhibits positive CD200 expression in 95.5% of tumors." (PMID 37894750, 2023). "We found multiple UV target genes to be critical to the survival of skin cancer cells, including CD200, GJA5, GPR115, KLK7, SLAMF7 and SLP1." (PMID 28211524, 2017). "Several studies have examined the effect of CD200 expression on various types of skin cancer." (PMID 37894750, 2023). "CD200 expression has been well documented to exert adverse effects on clinical outcomes and has been identified as a negative prognostic factor for patients—a finding that persists across various lymphoproliferative disorders, solid tumors, and skin cancers." (PMID 38137547, 2023).
autoimmune encephalitis (2 papers, 2007 to 2023). Inflammation of the brain secondary to an immune response triggered by the body itself. "Absence of neuronal CD200 leads to an accelerated microglia response in both the facial nerve transection model and experimental autoimmune encephalitis." (PMID 18093340, 2007).
brain injury (2 papers, 2019 to 2025). Acute and chronic (see also brain INJURIES, CHRONIC) injuries to the brain, including the cerebral hemispheres, CEREBELLUM, and brain STEM. "This is consistent with our finding that CD49d is upregulated on circulating CD200R1-deficient monocytes and with earlier studies that have shown increased macrophage numbers in both sterile and autoimmune models of brain injury in CD200-deficient mice." (PMID 30777093, 2019). "Inflammation and hypoxia can induce CD200 expression, which further increases the immunomodulatory effects of MSCs and enhances their therapeutic potential for hypoxic-ischemic brain injury." (PMID 41221273, 2025).
colitis (2 papers, 2016 to 2021). Inflammation of the colon. "The disease activity index (DAI), which is based on the main features of colitis: weight loss, colon shortening, stool consistency, stool blood, and rectal bleeding, was decreased in Cd200−/− mice in comparison to WT mice (6.6 ± 0.4 vs. 8.7 ± 0.4, (p < 0.01, t-test)." (PMID 34069671, 2021). "Taken together, these data support the idea that over-expression of CD200 in CD200tg mice enhances CCR4 dependent Foxp3+ Treg cell migration to the colon in mice to suppress a chronic inflammatory response associated with chronic DSS colitis." (PMID 26841120, 2016). "Nevertheless these data are consistent with the hypothesis that acute DSS-induced colitis is mainly driven by innate immune mechanisms, and that CD200 can suppress the acute inflammatory response in association with reduction in infiltration of inflammatory cells." (PMID 26841120, 2016). "Concomitantly, DSS-induced colitis caused superficial inflammation of the colon with mucosal damage in DSS-treated WT and Cd200−/− mice." (PMID 34069671, 2021). "Upon induction of colitis, WT mice showed a mild infiltration of inflammatory cells into the mucosa, submucosa and muscular/serosa layers, whereas in Cd200−/− mice only the mucosal surface was infiltrated." (PMID 34069671, 2021). "In regard to the contribution of host microbiota on DSS-induced colitis, it is important to note that all mice used in our study were treated with a chronic regimen of doxycycline (needed to induce CD200-transgene expression in CD200tg)." (PMID 26841120, 2016). "We found that Cd200−/− mice displayed diminished severity of colitis when compared to WT mice." (PMID 34069671, 2021). "CD200 regulates the severity of DSS-induced colitis in conventionally-reared mice." (PMID 34069671, 2021). "Overall, these results suggest, that in conventionally reared mice lack of CD200 decreased susceptibility to chemically-induced colitis." (PMID 34069671, 2021). "The CD200:CD200R axis plays an immunoregulatory role in control of DSS induced colitis in mice." (PMID 26841120, 2016). "In contrast, in mice with chronic colitis, CD200 overexpression seems to exert a more important role in regulating Foxp3+ Treg levels/function to regulate colitis, likely through altering the molecular milieu (cytokines/chemokines) to regulate numbers/localization of Tregs." (PMID 26841120, 2016). "Thus, lack of CD200 may increase the suppressive activity of myeloid cells during colitis, which may explain why we see ameliorated colitis in Cd200−/− mice." (PMID 34069671, 2021). "To investigate whether CD200 affects the production of cytokines and chemokines in the experimental mice described we performed real time RT-PCR and multi-analyte Elisarray to compare the expression level of cytokines and/or chemokines in the four experimental groups of colitis." (PMID 26841120, 2016). "We show that by comparison with wild-type (WT) control mice, increased expression of CD200 provides protection from both acute and chronic colitis after DSS-induction, whereas severe colitis was seen in mice lacking either CD200 or CD200R1." (PMID 26841120, 2016). "Our studies investigated whether over-expression of CD200 could reduce inflammatory reactions in the colon and attenuate the severity of DSS-induced colitis under acute and/or chronic conditions in mice." (PMID 26841120, 2016).
dementia (2 papers, 2022 to 2024). Loss of intellectual abilities interfering with an individual's social and occupational functions. "Our findings included well-known dementia-associated protein biomarkers, such as BMP4, CD200, MANF, PLXNB1, PLXNB3, and SMPD1 for AD and BCAN, NCAN, and THY1 for VD, as well as uncovering novel proteins associated with AD or VD." (PMID 39226887, 2024). "At the protein level, we did not detect changes in CD200 expression in PD patients either, neither in the presence nor absence of dementia." (PMID 35296683, 2022).
depression (2 papers, 2023 to 2024). "Next, we examined the changes in CD200 mRNA levels in the medial prefrontal cortex (mPFC) and hippocampus, both of which were closely associated with stress and depression." (PMID 37391731, 2023). "Nevertheless, the association of CD200, microglia and neurogenesis in depression is unclear." (PMID 37391731, 2023). "Taken together, the development of depression is closely related to the activation of microglia and corresponding changes, and CD200/CD200R1 signaling plays an important role in maintaining microglia homeostasis." (PMID 37391731, 2023). "In the present study, we provided the evidence that CD200 exerted an antidepressant action in the mouse model of depression." (PMID 37391731, 2023). "Therefore, the effect and mechanisms of CD200 on depression were investigated." (PMID 37391731, 2023). "Thus, CD200 may serve as a potential target for the therapy of depression." (PMID 37391731, 2023). "Previous studies observed the changes in CD200 during stress, but the exact effect of CD200 on depression is not clear." (PMID 37391731, 2023). "However, the role of CD200/CD200R1 in depression is not currently known." (PMID 37391731, 2023).
ependymoma (2 papers, 2014 to 2019). A WHO grade II, slow growing tumor of children and young adults, usually located intraventricularly. "Because serum soluble CD200 (sCD200) levels correlated with tumor burden and overall survival in human ependymoma patients, we measured serum concentrations of CD200 in the canine patients; they appeared to be predictive of tumor progression in at least one case." (PMID 30682795, 2019). "The same trend may be true for ependymoma and medulloblastoma subsets, posterior fossa A and group 3 (cMYC+) subgroups, respectively, which are more aggressive, have low CD200 expression and exhibit high immune infiltrates." (PMID 25598973, 2014). "In our studies, we observed a positive correlation between soluble CD200 concentration and lineage negative MDSC expansion in both our GBM and ependymoma immunotherapy patients as they progressed and went off trial." (PMID 25598973, 2014).